RNU6-543P (RNA, U6 small nuclear 543, pseudogene)
Gene: Small nuclear RNA gene on chromosome 10 (63,110,139 to 63,110,246, forward strand). Ensembl gene ENSG00000199446.
Homologues: Orthologues: chimpanzee U6 (100% identical), macaque U6 (94% identical), pig U6 (81% identical), dog U6 (80% identical), guinea pig U6 (77% identical), dog U6 (76% identical), guinea pig U6 (67% identical), guinea pig U6 (66% identical). Paralogues in human: RNU6-1243P (88% identical), RNU6-1151P (87% identical), RNU6-1152P (86% identical), RNU6-379P (86% identical), RNU6-1060P (85% identical), RNU6-1251P (85% identical), RNU6-242P (85% identical), RNU6-43P (85% identical), RNU6-797P (85% identical), RNU6-1019P (84% identical), RNU6-1083P (84% identical), RNU6-199P (84% identical), and 1287 more.